ANXA2 (annexin A2)
Diseases named in the same sentence as ANXA2 in open-access papers (continued):
Sharing a sentence is not in itself a finding about the gene and the disease.
cancer (continued). "According to a systematic literature search, different cancers are characterized by ANXA2 dysregulation." (PMID 32823855, 2020). "Protein–protein interaction analysis of common DEGs in L. brandtii showed that the most significant core genes were CXCL1, MMP9, JUN, ANXA2, and F5, which regulate immune response and cancer progression." (PMID 32256671, 2020). "A number of gene nodes linked to drug resistance in other cancer types (including CAT, TRIM59, ANXA2, ADM, AJUBA, HSPA1A/1B, LAMC2, TRIM14, KRT8, KRT18, KRT9, CLDN1, and SMARCA2) were also down-regulated in PARPis-sensitive AsPCs." (PMID 33213473, 2020). "Exo-AnxA2 showed diagnostic values with a maximum AUC as 1.000 for TNBC, 0.8304 for ER+, and 0.9958 for HER2+ compared to non-cancer females." (PMID 31992335, 2020). "Although the methods used for assessing EMT vary, many come to the consensus that Annexin A2 plays a role in triggering the mesenchymal and migratory phenotype in cancer cells via the transcriptional program of EMT." (PMID 32629869, 2020). "Our present study also indicates a strong association of exo-AnxA2 with TNBC in comparison to ER+, HER2+, and non-cancer females." (PMID 31992335, 2020). "The diagnostic ability of serum exo-AnxA2 was also evaluated in ER+ (n = 50), HER2+ (n = 59), and TNBC (n = 58) patients compared to non-cancer (n = 68) patients." (PMID 31992335, 2020). "RT-qPCR was used to analyze the level of ANXA2 mRNA in core biopsy tissue samples (normal = 5, cancer = 30)." (PMID 32629869, 2020). "In conclusion, this study has revealed that HE4 is expressed in several malignant tumor types where it interacts with ANXA2 to facilitate invasion, migration, adhesion, and proliferation." (PMID 31210752, 2019). "To investigate the role of ANXA2 in the regulation of EGF/EGFR signaling, we established cancer cell lines depleted of ANXA2 (A549, HT1080 and MDA-MB-231 ANXA2 knockdown (KD)) and respective controls (ANXA2 scramble)." (PMID 30959964, 2019). "With this work, we show for the first time, that depletion of ANXA2 in cancer cells leads to enhanced activation of AKT in response to either EGF/EGFR activation or oncogenic H-RasV12 transformation." (PMID 30959964, 2019). "We found that high expression of ANXA2 can increase the mobility of cancer cells from TCGA datasets." (PMID 31186633, 2019). "Higher levels of AnxA2, in association with STAT3, regulates proliferation, invasion, and migration of cancer cells." (PMID 31552186, 2019). "Consistent with other studies, we have proven that Anxa2 Tyr23 phosphorylation is critical in the invasion and metastasis of many types of cancer." (PMID 31113450, 2019). "Overall, we aime to provide a comprehensive evidence for the expression and biological functions of HE4 and ANXA2 in malignant tumors." (PMID 31210752, 2019). "The results showed that HE4 and ANXA2, both located in the membrane and cytoplasm, were highly expressed and widely interacted in various malignant tumor cells." (PMID 31210752, 2019). "HE4 and ANXA2 can synergistic promote the proliferation, adhesion, invasion, and migration of cancer cells." (PMID 31210752, 2019). "In this study, we showed that the ANXA2-expressing Listeria-based immunotherapy suppresses both primary PDACs and liver metastases, further supporting the notion that ANXA2 is a target for anti-cancer immunotherapy." (PMID 31113479, 2019). "The authors also show that PRDX2 was not able to bind to PTEN, which is in agreement with our results, demonstrating that PRDX2 up-regulation is not able to impede the enhanced AKT phosphorylation observed upon depletion of ANXA2 in cancer cells." (PMID 30959964, 2019). "Recent studies have revealed that Annexin A2 (Anxa2) is a key protein that links drug resistance and cancer metastasis." (PMID 31113450, 2019). "Together these results suggest that a threshold for ANXA2 depletion is required to trigger PRDX2 up-regulation in cancer cells." (PMID 30959964, 2019).
cancer (continued). "This evidence suggests that Anxa2 is a key protein that links drug resistance and cancer metastasis." (PMID 31113450, 2019). "ANXA2 is upregulated in many cancer types and is involved in cancer cell migration, adhesion, invasion, and metastasis." (PMID 31731625, 2019). "ANXA2 is an annexin family member, and has been found to interact with various ligands, and moreover is involved in the development of diverse cancers." (PMID 31695759, 2019). "The antigen target was subsequently found to be Annexin A2, an oncofetal antigen expressed on both embryonic cells and cancer cells." (PMID 31388993, 2019). "We developed a Listeria-based, ANXA2-targeting cancer immunotherapy (Lm-ANXA2) and investigated its effectiveness within two murine models of PDAC." (PMID 31113479, 2019). "Several studies have shown that chemotherapeutic agents can enhance phosphorylation of Anxa2 in cancer cells, and anti-cancer drugs have been shown to induce highly aggressive phenotypes in resistant cells." (PMID 31113450, 2019). "Our findings suggest a convergence point role of Rack1/Src/Anxa2 complex in the crosstalk between drug resistance and cancer aggressiveness." (PMID 31113450, 2019). "Unlike these reports, our data suggested that surface expression of a glycoform of ANXA2 is uniquely present on cancer cells prior EMT transformation." (PMID 29568351, 2018). "ANXA2 (Annexin A2) is a pleiotropic calcium-dependent phospholipid binding protein that is abnormally expressed in various cancers." (PMID 30081903, 2018). "ANXA2-coated enlargeosomes exocytose chemotherapeutic drugs to decrease the level of chemotoxicity in cancer cells." (PMID 29598816, 2018). "In cancer cells, increased annexin A2 and S100A10 expression result in increased plasmin production, which leads to the degradation of the ECM and activation of MMPs, thereby enabling the invasion of surrounding organs or local vasculature." (PMID 30572596, 2018). "In line with our findings, overexpression of ANXA2 has been demonstrated to facilitate cancer cell migraton, invasion and metastasis in the majority of cancer types." (PMID 30081903, 2018). "ANXA2 over expression has been reported in cancers of the breast, liver, prostate and pancreas, where it plays role in cancer cell migration, invasion, metastasis and adhesion." (PMID 30517191, 2018). "Second, the abnormal up-regulation of Annexin A2 enhances cancer development with higher aggression and poorer prognosis." (PMID 29508276, 2018). "Weihua Qiu and his colleagues performed a meta-analysis of 2321 cancer patients to confirm that high expression of ANXA2 was correlated with both OS (hazard ratio [HR] 1.56; p < 0.001) and disease-free survival (HR 1.47; p < 0.001)." (PMID 29598816, 2018). "miR-206 is downregulated in many cancers and has been shown to target K-Ras, annexin a2, and cell cycle genes." (PMID 30087365, 2018). "In this review, cellular and molecular mechanisms of ANXA2-mediated cancer progression and therapeutic resistance are addressed in the first two sections." (PMID 29598816, 2018). "The levels of Anxa2 and its Tyr23-phosphorylated form increase in several cancers, and the protein is involved in malignant cell transformation, metastasis, and angiogenesis." (PMID 29643068, 2018). "Altogether, these studies suggest that ANXA2 can be used as a prospective biomarker and therapeutic target for cancer treatment." (PMID 30081903, 2018). "In recent years, increased attention has focused on ANXA2 and its role in regulating cancer development." (PMID 29598816, 2018). "First, an accumulating observations have shown that Annexin A2 overexpressed in various types of cancer cells such as hepatocellular carcinoma, breast cancer, lung cancer, gastric carcinoma, pancreatic cancer, and colorectal cancer." (PMID 29508276, 2018).
cancer (continued). "G-Rg5 and G-Rk1 triggered multiple cellular events, which possibly participated in NF-κB activation, however, this activation was dominantly inactivated by G-Rg5 or G-Rk1 binding to Annexin A2-WT in Annexin A2 over-expressed cancer cells." (PMID 29508276, 2018). "Targeting ANXA2 raises the possibility of being able to overcome the low therapeutic efficacy of cancers with high ANXA2 expression." (PMID 29598816, 2018). "These conflicting reports provide further evidence that the role of ANXA2 in cancer-related EMT has yet to be fully elucidated." (PMID 29568351, 2018). "In the previous section on aberrant expression in cancers, we described how ANXA2 can be a novel marker to detect circulating CSCs in the clinic; however, the role of ANXA2 in CSCs is not yet clearly understood." (PMID 29598816, 2018). "Consistently, MYC is associated with the invasion and metastasis potential of multiple types of cancer cells, and it can be upregulated by ANXA2." (PMID 30081903, 2018). "The annexin A2/S100a10 complex has been reported as being upregulated in many cancers, including HCC." (PMID 28179399, 2017). "Preclinical studies have revealed a functional role for extracellular annexin A2 in the regulation of adhesion, migration, homing, and invasion of cancer cells." (PMID 28652618, 2017). "The authors reported a global decrease in miRNA loading to cancer cell EVs upon Annexin A2 silencing." (PMID 28360889, 2017). "Annexin A2 is over-expressed in several cancer cell lines, and it promotes cancer cell survival and metastasis." (PMID 28963461, 2017). "The upregulation of annexin A2 in various cancers is 5.74, the metastatic HMPOS show values of 8.63." (PMID 28910304, 2017). "By screening for molecules that interact with (20S)G-Rh2 in a phage display assay, we have identified Annexin A2 as a potential target that mediates its anti-cancer activity." (PMID 28963461, 2017). "Inactivating of Annexin A2 inhibits cancer cell proliferation and metastasis and sensitizes cancer cells to anti-cancer drugs." (PMID 28963461, 2017). "Our next goal was to provide evidence for the notion that Annexin A2 is an important target protein of (20S)G-Rh2 to execute its anti-cancer activity." (PMID 28963461, 2017). "To study Annexin A2-mediated anti-cancer activity of (20S)G-Rh2, we conducted MTT and plate clone formation assay." (PMID 28963461, 2017). "Validation studies revealed that cyclophilin A, annexin A2, and aldolase A expression levels were significantly higher in cancer compared to non-cancer regions." (PMID 27468721, 2016). "Due to this reported function, several studies suggested ANXA2 as an essential regulator of cancer cell adhesion and invasion, but also proliferation." (PMID 27429043, 2016). "Fructose-bisphosphate aldolase A (aldolase A), peptidyl-prolyl cis-trans isomerase A (also known as cyclophilin A), and annexin A2 were upregulated in cancer regions and consequently selected as candidate diagnostic biomarkers." (PMID 27468721, 2016). "As suggested in the network construction, the optimized minimum networks pinpoint three chemoresistance markers, namely protein DJ-1, annexin-A2, and prohibitin, which have shown close relationship to chemoresistance in various types of cancer." (PMID 27845899, 2016). "In contrast, ANXA2 expression was lower in cancer tissues than that in normal tissues (mean histoscores; 94 vs. 133, p = 0.002)." (PMID 27402115, 2016). "Given the role of Annexin A2 in regulation of cancer development, we here focus on the relationship between Annexin A2 and UBAP2." (PMID 27121050, 2016). "ANXA2 expression is elevated in many tumors, and in many cancers high levels of ANXA2 portend a poor prognosis." (PMID 26885373, 2016). "This study showed that the growth of tumors derived from annexin A2 depleted cancer cells was significantly impaired compared to tumors derived from control cancer cells (expressing normal levels of annexin A2)." (PMID 26682014, 2016).
cancer (continued). "AnxA2 is upregulated in several cancer types and in some cancer cell lines only phosphorylated AnxA2 is detected, supporting a role for AnxA2 phosphorylation in cell survival and proliferation." (PMID 26644180, 2016). "Accumulating evidence have showed that Annexin A2 is aberrantly expressed in a wide spectrum of cancers, including HCC." (PMID 27121050, 2016). "It has been reported that annexin 2A (ANXA2) expression is highly up-regulated in many types of cancer, and the molecular target for Ni (II) toxicity." (PMID 27626938, 2016). "In mesenchymal-like SK-BR-3 cells, Anxa2 was expressed at a low level, but the expression level of its tyrosine phosphorylation was significantly increased, which plays a critical role in cancer cells EMT and metastasis." (PMID 26307676, 2015). "In conclusion, our findings demonstrate that ANXA2 promotes therapeutic tolerance and multiple malignant phenotypes, including migration, invasion, epithelial-mesenchymal transition, and cancer stemness." (PMID 26196246, 2015). "Phosphorylation at tyrosine 23 plays a crucial role for Anxa2 in promoting cancer cell migration, invasion and metastasis." (PMID 26307676, 2015). "ANXA2 has been proven to stimulate the proliferation, invasion, and metastasis of cancers, including ovarian, hepatocellular, glioma, pancreatic, and breast cancers." (PMID 26196246, 2015). "ANXA2 heterotetramers are localized on the cell surface of endothelial cells and in several types of cancers." (PMID 25611381, 2015). "Here, we found that silencing of ANXA2 reduced cancer stem cell formation ability and expression of CSC associated markers Oct4, Sox2 and Nanog." (PMID 26196246, 2015). "Basing on these findings, we suppose that the direct binding of Anxa2 to STAT3 facilitates STAT3 activation in cancer cells." (PMID 26307676, 2015). "The expression of ANXA2 is significantly increased in the malignant tumors of the blood, and breast, cervical, and pancreatic cancers, and is also related to drug resistance and poor prognosis." (PMID 26362938, 2015). "The role of AnxA2 in the carcinogenesis of human cancers is still debated as it has been shown to be overexpressed in some cancers and downregulated in others, both of which have been identified as beneficial to cancer cells depending on location." (PMID 25290763, 2015). "ANXA2 has a critical role in the progression and metastasis of a variety of tumors, and it is therefore considered to be a potential therapeutic target in cancer." (PMID 25611381, 2015). "Annexin A2 is also involved in mammalian cell cycle regulation, and its levels are enhanced in many cancers." (PMID 25806802, 2015). "Annexin A2 overexpression has been described in many cancers, including liver, lung and kidney cancers." (PMID 25641213, 2015). "Recently, the potential role of ANXA2 in immunology gives a hint on the interaction between immune cells and cancer cells in the microenvironment." (PMID 24591759, 2014). "Annexin A2 (ANXA2) orchestrates multiple biologic processes and clinical associations, especially in cancer progression." (PMID 24591759, 2014). "With some cancers, ANXA2 can be used for the detection and diagnosis of cancer and for monitoring cancer progression." (PMID 24591759, 2014). "In this paper, we summarize the expression and structure of ANXA2 as well as its function in cancer cells or primary cancer tissues." (PMID 24591759, 2014). "This review discusses the feasibility of ANXA2 which is active in cancer development and can be a therapeutic target in cancer management." (PMID 24591759, 2014). "Conversely, annexin A2, well known to have multiple functions and biological role in cancer cells, also requires S100A10 for its action and translocation to the cell surface." (PMID 24851084, 2014). "Several studies reported an increased expression of Annexin A2 in cancer tissues compared to normal tissues." (PMID 24489826, 2014).
cancer (continued). "ANXA2 is overexpressed strongly in the cell membrane of primary cancer cells and weakly in the cytoplasm of carcinoma cells." (PMID 24591759, 2014). "We decided to study one of these aptamers, named ACE4, and we identified that it binds to the Annexin A2, a protein overexpressed in many cancers." (PMID 24489826, 2014). "ANXA2 is also expressed on the surface of several types of cancer cells and plays a role in migration and invasion." (PMID 24465474, 2014). "Investigation of the proteins were associated with incidence of cancers, including ZAG, CALR, annexin A2, annexin A3 and Hp." (PMID 24884814, 2014). "A proteomics study showed a 2.3-fold increase in annexin A2 protein levels in the nucleus of A549 cancer cells infected with RSV compared to uninfected cells." (PMID 23434659, 2013). "Many studies have attributed the role of plasmin generation and cancer cell invasion to annexin A2 (discussed next)." (PMID 23519104, 2013). "Chlorotoxin (CTX) is a scorpion-derived disulfide-rich peptide that targets malignant tumors by binding the cell surface matrix metalloproteinase-2 and annexin A2." (PMID 24137314, 2013). "Quantitative analysis showed that annexin A2 antibody significantly inhibited OV-90 cancer cell invasion into the CAM mesoderm." (PMID 23945256, 2013). "Annexin A2 is present in various cells such as endothelial cells, monocytes, macrophages and most cancer cells." (PMID 23519104, 2013). "Our results provided an explanation for this observation, since annexin A2 antioxidant function will protect the cancer cells from oxidative damage/death induced by the chemotherapeutic agents." (PMID 23434659, 2013). "Accumulating evidence delineates a correlation between the deregulation of annexin A2 expression and tumorigenesis in many cancers but disregard the possible role of S100A10." (PMID 23519104, 2013). "Here, we will describe in detail the role of annexin A2 in cancer progression, inflammation and anti-phospholipid syndrome (APS)." (PMID 23519104, 2013). "Recent studies have shown changes in the redox status of annexin A2 under oxidative stress conditions, including cancer." (PMID 23434659, 2013). "Treatment with annexin A2 antibody resulted in a 3.6 fold reduction in cancer cell invasion, compared with OV-90 cancer cells treated with mouse IgG antibody (P = 0.004, Mann-Whitney U test)." (PMID 23945256, 2013). "Annexin A2 also negatively correlated with the differentiation status of ESCC tumors with less differentiated malignant tumors having the lowest annexin A2 levels suggesting a role of annexin A2 in ESCC malignant progression." (PMID 23519104, 2013). "Most studies have reported that annexin A2 expression is elevated in many cancers and can directly correlate with clinical outcome." (PMID 23519104, 2013). "This surface-localized AnxA2, along with its binding partner, then leads to degradation of extracellular matrix and helps in migration and invasion of cancer cells." (PMID 22957061, 2012). "Subsequently, AnxA2 is known to be involved in actin polymerization, which consequently also helps in migration of cancer cells." (PMID 22957061, 2012). "Since Anxa2 is overexpressed in invasive tumors and plays an important role in cancer progression and invasion." (PMID 23691485, 2012). "Our results provide an explanation for this observation, since ANXA2 antioxidant function will protect the cancer cells from oxidative damage/death induced by the chemotherapeutics." (PMID 22185818, 2011). "Collectively, these results support a role for ANXA2 in cancer cell redox regulation during tumorigenesis." (PMID 22185818, 2011). "ANXA2 also functionsas a high-affinity receptor for multiple extracellular ligands that have beenimplicated in cancer development, invasion, and metastases." (PMID 21572519, 2011). "ANXA2 is reported to be overexpressed in a variety of cancers including PDA whencompared with normal tissues." (PMID 21572519, 2011).